ERLIN1 (ER lipid raft associated 1)
Diseases named in the same sentence as ERLIN1 in open-access papers:
ERLIN1 is named in the same sentence as 36 diseases in open-access papers, as found by Europe PMC text mining. Sharing a sentence is not in itself a finding about the gene and the disease. The quoted sentences say what the papers report.
viral infections (6 papers, 2017 to 2023). "report that Usp25, a deubiquitylase, is able to restrict virus infection by stabilizing the Erlin1/2 complex, which in turn regulates intracellular cholesterol levels." (PMID 37683630, 2023). "Despite these numbers of reports have illustrated the role of Erlin1 cell fate, metabolism or virus infection, limited studies are aimed to explore the role of Erlin1 in cancer development." (PMID 35412433, 2022). "However, recent advances have indicated that the ERLIN1/2 complex regulates calcium channeling, cell cycle progression, and cholesterol homeostasis of the cell, playing a role in the regulation of viral infections." (PMID 34572057, 2021). "Since Erlin1/2 were initially identified as B12-interacting partners, we asked if B12’s ability to interact with Erin1/2 enables B12 to mobilize into the foci in order to support viral infection." (PMID 28614383, 2017). "Interestingly, Inoue and Tsai reported a link between ERLIN1/2 and viral infections." (PMID 34572057, 2021). "ERLIN1 expression was increased in neonates with necrotizing colitis or bacterial infection, but not in neonates with viral infections (GSE25504-6947, GSE25504-13667)." (PMID 34439987, 2021).
hereditary spastic paraplegia (4 papers, 2019 to 2025). Hereditary spastic paraplegias (HSP) comprise a genetically and clinically heterogeneous group of neurodegenerative disorders characterized by progressive spasticity and hyperreflexia of the lower limbs. "Mutations in genes encoding the neuronal isoform of the inositol 1,4,5-trisphosphate receptor (ITPR1) and genes involved in inositol 1,4,5-trisphosphate receptor degradation (ERLIN1, ERLIN2) are known to cause hereditary spastic paraplegia (HSP) and cerebellar ataxia." (PMID 31636353, 2019).
breast carcinoma (3 papers, 2014 to 2023). "In breast cancers, ERLIN1 was discovered to be targeted by estrogen/MYC/miR-26 axis and promote cell growth." (PMID 38268722, 2023).
Cognitive impairment (2 papers, 2019 to 2020). Abnormal cognition is characterized by deficits in thinking, reasoning, or remembering. "For example, loss of function of Erlin1 and Erlin2, mutated in SPG62 and SPG18, respectively, are responsible for early onset autosomal recessive HSP associated with cognitive impairment." (PMID 32180696, 2020).
influenza (2 papers, 2022 to 2023). An acute viral infection of the respiratory tract, occurring in isolated cases, in epidemics, or in pandemics; it is caused by serologically different strains of viruses (influenzaviruses) designated A, B, and C, has a 3-day incubation period, and usually lasts for 3 to 10 days. "To determine how Usp25-Erlin1/2 restricted influenza infection, we first generated shRNA-mediated depletions of Erlin1, Erlin2, and a combination of Erlin1/2." (PMID 37683630, 2023). "Erlin1 is also correlated with hepatitis C virus infection and may have the potential to be targeted for the development of vaccine, such as hepatitis C virus vaccine and influenza vaccine." (PMID 35412433, 2022).
pancreatic adenocarcinoma (2 papers, 2018 to 2023). "In addition, ERLIN1 had a diagnosis value and associated with the survival time of pancreatic adenocarcinoma patients." (PMID 29596435, 2018). "Herein, we first found that the expression of ERLIN1 was positively related to tumor differentiation of pancreatic adenocarcinoma." (PMID 29596435, 2018). "Moreover, in pancreatic adenocarcinoma, higher expression of ERLIN1 was correlated with poor survival and lower CD8+T cell infiltration." (PMID 38268722, 2023). "Finally, 8 differentially expressed genes (ERLIN1, HMGA2, FAM110B, EGFR, MCM2, BCL2L1, E2F1 and RAC1) were considered to be significantly negatively associated with survival (P < 0.05) time of pancreatic adenocarcinoma patients." (PMID 29596435, 2018). "Therefore, we concluded that ERLIN1 played crucial roles in tumor differentiation and could be a diagnosis and prognosis marker for pancreatic adenocarcinoma." (PMID 29596435, 2018). "Among these genes, JUB, ERLIN1, FAM110B, MCM2 and BCL2L1 also had a diagnosis value for pancreatic adenocarcinoma." (PMID 29596435, 2018).
pancreatic cancer (2 papers, 2020 to 2022). "Based on the HPA database, immunohistochemistry suggested that CAST, CCDC6, and ERLIN1 protein expression was lower in normal pancreatic tissues but higher in pancreatic cancer tissues." (PMID 35938160, 2022).
Spastic paraplegia (2 papers, 2023 to 2024). Complete loss of the ability to move the lower limbs accompanied by spasticity of the lower limbs. "In contrast, overexpression of wild-type Erlin1/2 resulted in significantly reduced virus production, whereas a spastic paraplegia-linked mutant variant (ErlinT65I) did not affect virus production, confirming its role as a virus restriction complex." (PMID 37683630, 2023). "A Gly50Val substitution in ERLIN1 has been implicated in autosomal recessive SPG62, whereas His50Tyr (ClinVar ID: 947803) and Arg36Lys (ClinVar ID: 1720746) in ERLIN2 have been reported as a variant of unknown significance in individuals with spastic paraplegia." (PMID 38782601, 2024).
Aphasia (1 paper, 2021). An acquired language impairment of some or all of the abilities to produce or comprehend speech and to read or write. "ERLIN1 mutations have also been reported in HSP complicated by intellectual disability and aphasia." (PMID 34946884, 2021).
cervical cancer (1 paper, 2020). A primary or metastatic malignant neoplasm involving the cervix. "Our results also showed that the protein expression of MGST3, AKR1C2, and ERLIN1 decreased in cervical cancer cells in the presence of AS-IV." (PMID 32265995, 2020).
coronary artery disease (1 paper, 2017). "In conclusion, we discovered and confirmed a gain of the 10q24.31 (ERLIN1) and 12q24.11 (UNG, ACACB) genomic regions in patients with coronary artery disease and metabolic comorbidity." (PMID 28120895, 2017).
distal myopathy (1 paper, 2021). Distal myopathy refers to a group of muscle diseases which share the clinical pattern of predominant weakness and atrophy beginning in the feet and/or hands. "Other allelic neurological disorders with the same gene associations are ataxia with oculomotor apraxia (SETX), HSP (ALS2, SPG11, ERLIN1, and DDHD1), JPLS (ALS2), dHMN (SIGMAR1), distal myopathy (GNE), and distal SMA (BICD2)." (PMID 34946884, 2021).
gastric carcinoma (1 paper, 2018). A carcinoma that arises from epithelial cells of the stomach. "It is reported that the expression of ERLIN1 is decreased in laser capture microdissection gastric carcinomas compared to histologic macrodissection." (PMID 29596435, 2018).
psoriasis (1 paper, 2021). An autoimmune condition characterized by red, well-delineated plaques with silvery scales that are usually on the extensor surfaces and scalp. "A recent trans-disease meta-analysis revealed four co-regulated loci between psoriasis and type 2 diabetes, one of which corresponded to the ERLIN1 gene; the resulting proteins are connected through the NF-κB signaling pathway." (PMID 34439987, 2021).
Sepsis (1 paper, 2021). Sepsis is defined as life-threatening organ dysfunction caused by a dysregulated host response to infection. "Our findings suggest a novel association between ERLIN1 and sepsis." (PMID 34439987, 2021). "We replicated the induced expression of ERLIN1 observed during sepsis by using in vitro models exposed to a combination of lipopolysaccharide (LPS) and peptidoglycan (PGN)." (PMID 34439987, 2021). "The current available studies on ERLIN1 and sepsis indicate a knowledge gap between the functions of ERLIN1, calcium balance, and cholesterol and fatty acid synthesis, and sepsis." (PMID 34439987, 2021). "The scarcity of ERLIN1 in sepsis literature indicates a knowledge gap between the functions of ERLIN1, calcium homeostasis, and cholesterol and fatty acid biosynthesis, and sepsis." (PMID 34439987, 2021). "Calcium flux, ER stress, ubiquitin-mediated protein degradation, and lipid membrane modularity are processes and concepts known to be influenced by ERLIN1, and are indicative of the potential roles of ERLIN1 induction in the context of sepsis." (PMID 34439987, 2021). "Using such resources, we observed a consistent increase in ERLIN1—a gene coding for an ER membrane prohibitin and regulator of cholesterol—in whole blood, and across a variety of immune cells, during sepsis or sepsis-like conditions." (PMID 34439987, 2021). "Thus, the described biological functions of ERLIN1 suggest potential roles for its expression during sepsis in ER-mediated protein degradation, cholesterol homeostasis, and signaling events through lipid membrane structures and inositol pathways." (PMID 34439987, 2021). "Together with experimental data, we think that ERLIN1 is modulated differently in immune cells in response to infection, and has important implications for ER functions and/or ER membrane protein components during sepsis." (PMID 34439987, 2021). "As the ERLIN complex is known to affect the stability of some model ERAD substrates, increased ERLIN1 during the acute phase of sepsis may triage proteins for secretion or degradation." (PMID 34439987, 2021). "The presumed bridge between sepsis and ERLIN1 is supported by the characteristically low levels of high-density lipoprotein cholesterol (HDL-C) and triglycerides observed in the plasma of septic patients, which are strongly associated with risk of adverse outcome." (PMID 34439987, 2021). "A thorough investigation of the role of ERLIN1 may provide novel insights into the connection between intracellular Ca2+ and cholesterol homeostasis and the pathogenesis of sepsis." (PMID 34439987, 2021). "Although our literature mining and experimental evidence points to the putative impact of ERLIN1 in the pathogenesis of sepsis, its roles in the interplay between intracellular Ca2+ release and IP3R degradation as well as cholesterol depletion during sepsis remain a matter for educated speculation." (PMID 34439987, 2021). "Although there was no direct overlap between the ERLIN1 and sepsis literature, the two may be linked by intermediate biological concepts, such as those linking ERLIN1 with inflammatory processes." (PMID 34439987, 2021). "In combination with experimental data, we bring forth the hypothesis that ERLIN1 is variably modulated among immune cells in response to cellular perturbations, and has implications for ER functions and/or ER membrane protein components during sepsis." (PMID 34439987, 2021). "Moreover, similar increases in ERLIN1 expression in sepsis were also observed in other transcriptome datasets obtained from whole blood (n = 8) and isolated cell (n = 8) samples, and generated from in vivo (n = 5), ex vivo (n = 1), and in vitro (n = 8) experimental designs." (PMID 34439987, 2021). "We observed an increase in ERLIN1 in whole-blood neutrophils and HL60 cell lines during sepsis; however, the protein was expressed differently in other immune blood cells." (PMID 34439987, 2021).
steatosis (1 paper, 2016). Increased lipid within the cytoplasm of cells. "Conversely, serum miRNAs associated with blunt steatosis specifically highlighted activity of FOXO1&HNF4α on CPT2, the lipid droplet and ER-lipid-raft associated PLIN3 and Erlin1." (PMID 27045805, 2016).
tuberculosis (1 paper, 2021). A chronic, recurrent infection caused by the bacterium Mycobacterium tuberculosis. "While the role of ERLIN1 in cancer and tuberculosis is undefined, these observations suggest that ERLIN1 may be an indicator of the disrupted intracellular environment in disease states." (PMID 34439987, 2021). "Non-septic stress can also induce ERLIN1 expression, as seen in monocytes from healthy donors, patients with metastatic breast cancer or tuberculosis (GSE65517)." (PMID 34439987, 2021).
infection (6 papers, 2017 to 2023). The state of being infected such as from the introduction of a foreign agent such as serum, vaccine, antigenic substance or organism. "Importantly, as reconstituting either Erlin1 or Erlin2 fully restored the infection block caused by silencing Erlin1/2, these related membrane proteins likely execute overlapping functions during SV40 infection." (PMID 28614383, 2017). "Silencing of erlin-1 protein expression by siRNA led to decreased infection efficiency characterized by reduction in intracellular RNA accumulation, HCV protein expression and virus production." (PMID 31810281, 2019). "Mechanistic studies revealed that erlin-1 protein is required early in the infection, downstream of cell entry and primary translation, specifically to initiate RNA replication, and later in the infection to support infectious virus production." (PMID 31810281, 2019). "While depleting either Erlin1 or Erlin2 individually blocked infection moderately (compare second and third to first bar), simultaneous knockdown of Erlin1/2 potently reduced SV40 infection (compare fourth to first bar)." (PMID 28614383, 2017). "Indeed, ERLIN1 is considered a host factor required for HCV life cycle; depletion of ERLIN1 leads to a decreased infection efficiency." (PMID 34572057, 2021). "Due to its ER location and effect on membrane composition, the involvement of ERLIN1 may be dependent on the type of infection." (PMID 34439987, 2021). "Within this report we have extended our list of host proteins co-localizing within the WNVKUN RC and show that two host proteins known to associate with “lipid raft-like,” cholesterol-rich domains within the ER, erlin-1 and erlin-2, co-locate with dsRNA during infection." (PMID 34055786, 2021). "A quantitative analysis of the localization of core and NS5A proteins surrounding LDs confirmed that the reduced infectious virus accumulation observed in ERLIN1-deficient cells was not due to a mislocalization of core or NS5A proteins during infection." (PMID 31810281, 2019). "Single cycle infection experiments in ERLIN1 down-regulated cells showed a modest 2–3 fold reduction in intracellular HCV RNA accumulation compared to a ~4–10 fold reduction in HCV protein accumulation and ~10-fold reduction in intracellular infectious virus accumulation." (PMID 31810281, 2019). "Our study thus pinpoints Erlin1/2-dependent release as a key regulatory event enabling B12 to efficiently reorganize into the foci, where this J-protein facilitates virus ER membrane penetration leading to successful infection." (PMID 28614383, 2017). "Erlin1/2 support SV40-induced foci formation, and promote virus ER-to-cytosol transport, and infection." (PMID 28614383, 2017). "During infection, SV40 induces release of this J-protein from Erlin1/2 to enable B12 to reorganize into the foci." (PMID 28614383, 2017). "We conclude that Erlin1/2 play a pivotal function during SV40-triggered foci formation–this likely explains why Erlin1/2 are crucial for SV40’s ER-to-cytosol membrane transport leading to successful infection." (PMID 28614383, 2017). "They showed that erlin 1 and erlin 2 proteins are both required for polyomavirus SV40 infection by facilitating B12 transmembrane J-protein mobilization to specific foci in the ER, a prerequisite for the ER to cytosol transport of SV40, thus enabling the establishment of infection." (PMID 31810281, 2019).
tumor (4 papers, 2018 to 2022). "Recently, a study suggested that Erlin1 is dysregulated in different tumor differentiation grades, with diagnostic potential for pancreatic adenocarcinoma." (PMID 35412433, 2022). "Additionally, using WGCNA and machine learning, three diagnostic gene signatures (CAST, CCDC6, and ERLIN1) for the high level mitophagy subtype were obtained, which were closely associated with tumour immune microenvironment and chemotherapy sensitivity in PAAD." (PMID 35938160, 2022). "Collectively, these results suggest that matrine exerts its anti-tumor effect on CRC progression by decreasing Erlin1 expression." (PMID 35412433, 2022). "In the present study, we demonstrated that matrine exhibits potent anti-tumor activity by downregulating Erlin1 expression in CRC cells." (PMID 35412433, 2022). "The results suggested that Erlin1 knockdown enhanced the anti-tumor effects of matrine against CRC cells, which indicates that matrine suppresses CRC progression by regulating Erlin1 expression." (PMID 35412433, 2022). "Among the differentially expressed genes, Erlin1 was significantly downregulated upon matrine treatment in HT-29 cells, which may play important roles in matrine-mediated anti-tumor effects." (PMID 35412433, 2022). "When Erlin1 was knocked down, matrine exhibited a more obvious anti-tumor effect in CRC cells." (PMID 35412433, 2022). "Furthermore, the mRNA expression of CAST, CCDC6 and ERLIN1 could potentially predict the tumour’s sensitivity to Erlotinib, Sunitinib and Imatinib." (PMID 35938160, 2022). "The results suggested that the anti-tumor effect of matrine, including inhibition of cell proliferation, induction of cell apoptosis, and suppression of cell migration, could be strengthened by both matrine treatment and Erlin1 suppression." (PMID 35412433, 2022). "Moreover, PAAD tumours were insensitive to Erlotinib, Sunitinib and Imatinib in the high mitophagy subtype and high CAST, CCDC6, and ERLIN1 expressed subtypes." (PMID 35938160, 2022).
cancer (3 papers, 2020 to 2022). A tumor composed of atypical neoplastic, often pleomorphic cells that invade other tissues. "This study illustrated not only the oncogenic role of Erlin1 in CRC but also the contribution of Erlin1 to matrine’s anti-cancer effect." (PMID 35412433, 2022). "Since there are no studies reporting the role of Erlin1 on cancer, our study will be helpful for the research studies focusing on matrine, CRC diagnosis, or other CRC drugs." (PMID 35412433, 2022).
metabolic disease (2 papers, 2017 to 2023). A congenital disorder (due to inherited enzyme abnormality) or acquired (due to failure of a metabolically important organ) disorder resulting from an abnormal metabolic process. "Previous research has shown that common variants of the ERLIN1–CHUK-CWF19L1 gene cluster act in fatty liver and metabolic diseases." (PMID 37540242, 2023). "The mechanism of the increased copy number of ERLIN1 in regulating cellular cholesterol homeostasis in patients with coronary artery and metabolic diseases must be further elucidated in future studies." (PMID 28120895, 2017).
ERLIN1 also shares sentences with these, for which no sentence is quoted: adenoma (1 paper); amyotrophic lateral sclerosis (1); bacterial infection (1); cerebellar ataxia (1); colorectal cancer (1); gynecological tumor (1); Hepatic steatosis (1); Hepatitis (1); hepatitis C virus infection (1); Intellectual disability (1); intracerebral haemorrhage (1); neurological disorders (1); Onset (1); type 2 diabetes (1); zika virus infection (1).